S100A11 (S100 calcium binding protein A11)
Diseases named in the same sentence as S100A11 in open-access papers (continued):
Sharing a sentence is not in itself a finding about the gene and the disease.
ovarian carcinoma (continued). "Subsequently, the expression of S100A11 in ovarian cancer HO8910 cells was knocked down using short hairpin (sh)RNA in order to investigate the biological effects of S100A11 on the progression of the disease." (PMID 25780452, 2015). "Increased levels of S100A11 have been reported in ovarian cancer tissues, as compared with normal ovarian epithelial tissues." (PMID 25780452, 2015). "Additionally, FBXW11 facilitates the degradation of S100A11 via ubiquitination, thereby increasing the sensitivity of ovarian cancer cells to PARPi." (PMID 40747341, 2025). "To further determine whether FBXW11 affects ovarian cancer cell sensitivity to olaparib through S100A11, we introduced plasmids overexpressing S100A11 into HBLV group and HBLV FBXW11group." (PMID 40747341, 2025). "The combination of FBXW11 overexpression or S100A11 inhibition with PARPi might have great potential in the medical therapy of ovarian cancer." (PMID 40747341, 2025). "Thus, the knockdown of S100A11 expression suppresses ovarian cancer cell growth and invasion, and S100A3 expression is associated with chemoresistance of cancer cells." (PMID 38339228, 2024). "Knocking out the S100A11 gene could inhibit the growth, invasion, and migration of ovarian cancer cells." (PMID 33763485, 2021). "The expression levels of S100A11 were markedly increased in the ovarian cancer cell lines when compared with the ovarian surface epithelial cell line, indicating that S100A11 may play a role in the progression of ovarian cancer." (PMID 25780452, 2015). "Effects of S100A11 knockdown on the growth of ovarian cancer cells were examined using a cell growth assay, which revealed that knockdown of S100A11 inhibited the growth of ovarian cancer cells." (PMID 25780452, 2015). "In the present study, knockdown of S100A11 was found to suppress the invasion and migration of HO8910 cells, indicating that S100A11 may be involved in the regulation of ovarian cancer cell invasion and migration." (PMID 25780452, 2015). "Furthermore, the effects of S100A11 knockdown on the anchorage-independent growth of ovarian cancer cells were examined using a soft agar assay." (PMID 25780452, 2015). "Therefore, the aim of the present study was to analyze the levels of S100A11 in ovarian cancer cells." (PMID 25780452, 2015). "In addition, the effects of S100A11 knockdown on ovarian cancer cell growth and invasion were investigated in order to determine the function of S100A11 in ovarian cancer progression." (PMID 25780452, 2015). "However, there is a lack of relevant studies on the association between S100A11 and PARPi sensitivity in ovarian cancer." (PMID 40747341, 2025). "S100A11, also known as S100C or calgizzarin, has been reported to contribute to inflammatory processes and multiple neoplastic events in different types of cancers, including papillary thyroid cancer, ovarian cancer, cholangiocarcinoma, pancreatic carcinoma and gastric cancer." (PMID 33466593, 2021). "In addition, knockdown of S100A11 inhibited the invasion and migration of ovarian cancer cells, indicating that S100A11 may promote ovarian cancer cell invasion and migration via the regulation of E-cadherin and Snail expression." (PMID 25780452, 2015). "However, the function of S100A11 in ovarian cancer remains elusive." (PMID 25780452, 2015). "In order to determine whether S100A11 was associated with the invasion and migration of ovarian cancer cells, invasion and migration assays were conducted with mock-transfected control (Ctrl), negative control (NC) and S100A11 shRNA cells (sh#2)." (PMID 25780452, 2015). "Therefore, S100A11 may serve as a potential molecular target for the diagnosis and treatment of ovarian cancer." (PMID 25780452, 2015). "Our study in ovarian cancer demonstrated that FBXW11 increased the ubiquitination and degradation of S100A11, resulting in less efficient DNA damage repair and consequently heightened sensitivity to PARPi." (PMID 40747341, 2025).
ovarian carcinoma (continued). "Thus, S100A11 may play an important role in the progression of ovarian cancer." (PMID 25780452, 2015). "Thus, inhibition of S100A11 may provide a promising approach to the treatment of ovarian cancer." (PMID 25780452, 2015). "Expression levels of S100A11 in human ovarian surface epithelial cells (IOSE144) and ovarian cancer cells (A2780, OVCAR3, SKOV3 and HO8910) were determined using western blot analysis." (PMID 25780452, 2015). "Yet, S100A11 protein expression was markedly diminished in cells overexpressing FBXW11, whereas it was elevated in cells with FBXW11 knockdown, indicating a potential correlation between FBXW11 and S100A11 levels in ovarian cancer cells." (PMID 40747341, 2025). "Therefore, the joint analysis of S100A11 and MMP-9 is very important in the study of drug-resistance mechanisms in ovarian cancer." (PMID 33763485, 2021). "However, studies on the correlation between S100A11 and the sensitivity of ovarian cancer to PARPi are lacking." (PMID 40747341, 2025). "Therefore, inhibition of S100A11 and MMP-9 expression may further inhibit tumor invasion and metastasis, providing a promising direction in the diagnosis and treatment of ovarian cancer patients." (PMID 33763485, 2021). "The role of S100A11 in ovarian cancer has not been fully characterized." (PMID 25780452, 2015).
cervical carcinoma (8 papers, 2018 to 2025). A carcinoma arising from either the exocervical squamous epithelium or the endocervical glandular epithelium. "Meng et al34 reported that S100A11 can enhance the proliferation and invasion of cervical cancer cells." (PMID 39128058, 2024). "The overexpression of S100A11 can promote the proliferation and metastasis of cervical cancer cells." (PMID 36230965, 2022). "Studies have shown that the expression of S100A11 in cervical cancer tissue is significantly higher than that in paracancerous tissue and normal cervical tissue." (PMID 36230965, 2022). "S100A11 activates Wnt/beta-catenin Signaling and promotes proliferation and migration of cervical cancer cells." (PMID 33815482, 2021). "However, a study on cervical cancer also suggests that S100A11 upregulates N-cadherin while downregulates E-cadherin, implying that this may be common in several solid cancers." (PMID 33931048, 2021). "There are many subtypes of S100 calcium-binding protein, and several studies have found that S100A7, S100A9, S100A11, and S100A14 are closely related to cervical cancer." (PMID 36230965, 2022). "In HeLa cervical carcinoma cells, depletion of BCYRN1 disrupted the cellular motility by destabilizing mRNA for calcium-binding protein S100A11." (PMID 29435146, 2018). "Similarly to S100A2 and S100A11, S100A14 appears to have a complex role in cancer, showing overexpression in breast, liver and cervical cancer, but downregulation in other cancers such as rectal, kidney, colon and esophageal cancers." (PMID 37627239, 2023).
prostate carcinoma (8 papers, 2011 to 2025). A carcinoma that arises from epithelial cells of the prostate gland. "The up-regulation of S100A11 has been reported in various cancers, such as laryngeal, breast, lung, gastric, colorectal, pancreatic, and prostate cancers, and has frequently been associated with cancer progression, implicating its oncogenic role." (PMID 26544866, 2015). "Calcium entry provided by SOCE channels will allow for the TRPV6 translocation towards the plasma membrane by engaging Annexin1/S100A11 complex in prostate cancer cells." (PMID 32013022, 2020). "The aberrant cell surface expression of TRPV6 in prostate cancer is increased in prostate cancer cells via SOCE-dependent activation of the Annexin I/S100A11 complex." (PMID 32825277, 2020). "The Annexin1/S100A11 complex may vary depending on the tissue: Annexin1/S100A11 for the prostate cancer and S100A10/Annexin 2 complex in the intestine and the kidney." (PMID 32013022, 2020). "S100A11 and S100A10 are calcium binding proteins and their increased expression are often observed in colorectal and prostate cancer, including non-small cell lung cancer." (PMID 21909426, 2011).
rheumatoid arthritis (8 papers, 2017 to 2025). A chronic, systemic autoimmune disorder characterized by inflammation in the synovial membranes and articular surfaces. "S100A11 (calgizzarin), a member of S100 family, is associated with several autoimmune diseases, including rheumatoid arthritis (RA)." (PMID 33727634, 2021). "Specifically, we found enhanced levels of protein S100-A11 (calgizzarin) that has been identified as an inflammatory mediator associated with the disease activity of rheumatoid arthritis known to be an aggressive, cartilage and joint destructing pathologic agent." (PMID 37151865, 2023). "S100A11 has been reported to stimulate the production of the pro-inflammatory cytokine IL-6 by peripheral blood mononuclear cells (PBMC) and overexpression of S100A11 was associated with inflammation-related health problems such as osteoarthritis or rheumatoid arthritis." (PMID 36720844, 2023). "Among PSA T and NK cells, we also observed a downregulation of AP-1 transcription factors (JUN, JUNB, JUND, FOS) and regulators of activation (TNFAIP3, DUSP1) along with the upregulation of S100A11, a calcium-binding protein associated with rheumatoid arthritis." (PMID 35309349, 2022). "The aim of our study is to compare S100A11 expression in the synovial tissues, synovial fluid and serum of patients with rheumatoid arthritis (RA) and osteoarthritis (OA) and to characterize the potential association between S100A11 and disease activity." (PMID 28446208, 2017). "In the synovial fluid of rheumatoid arthritis (RA) patients, S100A11 accumulates extensively and correlates with inflammation and disease progression." (PMID 40538500, 2025). "For example, S100A4 is involved in autoimmune pancreatitis, S100A11, S100A8 and S100A9 in rheumatoid arthritis, S100A1 in hypoxia-induced inflammatory response in cardiomyocytes, S100A12 in Crohn’s disease, S100A7 and S100A7A in psoriasis, S100A8, S100A9 and S100A12 in systemic lupus erythematosus." (PMID 30018736, 2018).
gastric cancer (7 papers, 2013 to 2025). A primary or metastatic malignant neoplasm involving the stomach. "High expression of S100A11 is associated with poor survival of gastric cancer patients (p < 0.001, HR = 1.85) and is an independent prognostic factor of gastric cancer." (PMID 33931048, 2021). "Similarly, S100A11 knockdown enhances the susceptibility of gastric cancer to 5-fluorouracil and cisplatin." (PMID 40747341, 2025). "The stable knockdown of S100A11 suppresses the metastatic properties of gastric cancer cells, which include enhancing cell adhesion, but decelerating cell migration and invasion." (PMID 33931048, 2021). "An unsupervised hierarchical clustering and principal component analysis (HCPC) was applied to unveil the dimensional role of S100A11 among all S100 family members in gastric cancer." (PMID 33931048, 2021). "To elucidate the function of S100A11, we knocked down this gene in gastric cancer cells and validated the knockdown efficiency by qPCR and Western blotting." (PMID 33931048, 2021). "Protein expression of S100A11 in gastric cancer was estimated by immunohistochemistry of a tissue microarray." (PMID 33931048, 2021). "And the initial molecule experiments also confirmed the consistency of p42.3 and S100A11 gene expression in gastric carcinoma cell." (PMID 26106439, 2015). "S100A11 was reported to be an accurate predictor of lymph node metastases in gastric cancer, and it was also reported to be a predictor of colon-derived liver metastases." (PMID 24376686, 2013). "Transcript levels of S100A11 in gastric cancer were evaluated using an in-house patient cohort." (PMID 33931048, 2021). "The present study identifies S100A11 as a tumour promoter in gastric cancer." (PMID 33931048, 2021). "Furthermore, the knockdown of S100A11 gene expression dramatically induces the cellular response of gastric cancer cells to the first-line chemotherapeutic drugs fluoropyrimidine 5-fluorouracil (5-FU) and cisplatin." (PMID 33931048, 2021). "Our experimental results present an upregulated expression of S100A11 in gastric cancer." (PMID 26106439, 2015). "There has been no previous study on the role of S100A11 in the regulation of E-cadherin/N-cadherin in gastric cancer." (PMID 33931048, 2021). "Through analysis of expression of S100A11 and S100A2 in gastric cancer, both of which contained EF-Hand structure, it was verified that p42.3 could participate in the occurrence and development of gastric cancer from both consistent and opposite to the p42.3 effect direction." (PMID 26106439, 2015).
colon carcinoma (6 papers, 2012 to 2025). "Several S100 proteins, including S100A1, S100A2, S100A4, and S100A11, were found in colon carcinomas with more aggressive disease and worse clinical outcomes." (PMID 41134679, 2025). "In conclusion, our study reveals that S100A11 is elevated in colon cancer tissues and correlates with immune cell infiltration and activity, suggesting its potential as a biomarker and target for treatment in colon cancer." (PMID 40567612, 2025). "In summary, these findings suggest that S100A11 is highly expressed in colon cancer and may play an important role in colon cancer progression." (PMID 40567612, 2025). "Pan-cancer analysis was first performed and revealed that S100A11 was differentially expressed in a variety of malignant tumor tissues, subsequent bioinformatics analysis using our TCGA-COAD dataset showed that S100A11 levels were notably increased in colon cancer tissues compared to normal tissues." (PMID 40567612, 2025). "Serum levels of CEA, IL-8, VEGF, S100A11, C3adesArg, CD26, MCSF and CRP showed significant differences between colon cancer cases and controls (P < 0.05)." (PMID 22954206, 2012). "Similarly, IHC staining showed a high amount of S100A11 protein expression in colon cancer tissues, while minimal staining was observed in adjacent normal tissues." (PMID 40567612, 2025).
non-small cell lung carcinoma (6 papers, 2011 to 2025). A group of at least three distinct histological types of lung cancer, including non-small cell squamous cell carcinoma, adenocarcinoma, and large cell carcinoma. "In non-small cell lung cancer, S100A11 knockdown significantly augments tumor sensitivity to cisplatin, oxaliplatin, and 5-fluorouracil." (PMID 40747341, 2025).
pancreatic ductal adenocarcinoma (6 papers, 2021 to 2025). An infiltrating adenocarcinoma that arises from the epithelial cells of the pancreas. "S100A11 was observed to be highly expressed in pancreatic ductal adenocarcinoma (PDAC) tissues and demonstrated a significant association with poorer prognosis and disease progression." (PMID 40221783, 2025). "Overexpression of S100A11 is associated with an unfavorable prognosis of patients with pancreatic ductal carcinoma undergoing surgical resection." (PMID 34804125, 2021). "However, in patients, high expression levels of S100A11 in pancreatic ductal adenocarcinoma have been associated with an unfavorable prognosis for patients who had undergone surgical resection." (PMID 37627239, 2023). "In pancreatic ductal adenocarcinoma, S100A11 bound to SMYD3 and then activated the expression of transketolase (TKT), thus stimulating pentose phosphate pathway to aggregate the malignant phenotypes." (PMID 37386026, 2023).
steatosis (6 papers, 2022 to 2025). Increased lipid within the cytoplasm of cells. "On the contrary, in vivo S100A11 downregulation in hepatocytes (by in vivo adenoviral transduction of hepatotropic AAV8 encoding S100A11 specific shRNA) restrained lipid accumulation in the liver of two mouse models of diet-induced steatosis." (PMID 36232334, 2022). "After 10 weeks of FPC diet, S100A10 or S100A11 knock-down reduced steatosis development, assessed by the measurement of liver triglyceride content and by automatic quantification of lipid droplets density on H&E coloration." (PMID 40841353, 2025). "Knock-down of S100A11 prevents steatosis as well as fibrogenesis in short-term high-fat-diet (HFD)/methionine-choline deficient diet feeding or in CCl4-induced MASLD mouse models." (PMID 40841353, 2025). "Next, we tested short-term/acute intervention on S100A10 or S100A11 for potential beneficial effects on steatosis reduction in an early phase by downregulating for only 1 month either S100A10 or S100A11 at 4 months of age." (PMID 40841353, 2025). "Supporting a pathological role of S100A11 upregulation in NAFLD, S100A11 overexpression in mice livers (by in vivo adenoviral transduction of hepatotropic associated-adeno viruses encoding S100A11 DNA, AAV8) fostered steatosis development." (PMID 36232334, 2022). "Indeed, as previously shown in other studies performed in high fat diet-induced MASLD models, preventive targeting S100A11 reduces steatosis." (PMID 40841353, 2025). "From 6 to 11 months of age, after steatosis development, LPTENKO mice were subjected to AAV8-based S100A10 or S100A11 downregulation." (PMID 40841353, 2025). "Sobolewski et al36 reported that S100A11/ANXA2 belongs to a tumor oncogene/tumor suppressor gene network, which can be deregulated through steatosis at an early stage, thereby participating in the development of inflammation and HCC." (PMID 39128058, 2024). "For example, upregulation of S100A11 and S100A8 expression was observed in the liver of NAFLD patients and various mouse models of obesity and/or steatosis, as well as in hepatocytes exposed to fatty acids, thus suggesting a strong implication of these two S100 isoforms in NAFLD development." (PMID 36232334, 2022).
liver cancer (5 papers, 2022 to 2025). An epithelial or non-epithelial malignant neoplasm that arises from the liver. "Some studies have observed that the increased expression of S100A11 in EIF3C exosomes promotes angiogenesis and both EIF3C and S100A11 are highly expressed in liver cancer, and their protein levels are associated with the low survival rate of patients with liver cancer." (PMID 37927791, 2023). "Next, we analyzed TCGA liver cancer cohorts and found that S100A11 mRNA expression was higher in HCC and was associated with poor HCC progression." (PMID 37166978, 2023). "TGF-β also promoted S100A11 expression in hepatic cancer cells such as Huh-7 and HepaRG, while growth factors also trigger S100A11 upregulation in Huh-7." (PMID 36232334, 2022). "However, these two closely associated proteins present opposite contributions to hepatic cancer, S100A10 being protective and S100A11 deleterious." (PMID 40841353, 2025). "In humans, S100A11 expression was also strongly correlated with the cancer stage, with the patient’s survival probability and secretion of this isoform by hepatic cancer cells highlighting S100A11 as a potential prognostic and diagnostic circulating biomarker for HCC." (PMID 36232334, 2022). "Here, we investigated the impact of hepatocyte downregulation of two closely-related members of the S100 family, S100A10 and S100A11, in complementary mouse models of MASLD and liver cancer." (PMID 40841353, 2025). "In concert with S100A11, ANXA2 is described as a driver of liver cancer and S100A10 controls the activity of ANXA2." (PMID 40841353, 2025). "To further confirm that PCK1 exerted antitumor effects through S100A11 suppression via upregulation of H3K9me3 modification in vivo, we developed a DEN/CCl4/PB-induced mouse model of liver cancer." (PMID 37166978, 2023). "Since etiology of liver cancer is multifactorial and multigenic, we next investigated the respective roles of S100A10 and S100A11 in an additional mouse model with or without the contribution of MASLD." (PMID 40841353, 2025). "As no rodent model faithfully recapitulate the whole complexity of human MASLD and HCC, we investigated the roles of S100A10 and S100A11 using complementary mouse models of MASLD, MASLD-driven HCC, or liver cancer without metabolic disorders." (PMID 40841353, 2025).